CXCL10 (C-X-C motif chemokine ligand 10)
Diseases named in the same sentence as CXCL10 in open-access papers (continued):
Sharing a sentence is not in itself a finding about the gene and the disease.
malaria (continued). "Additionally, we found that even in the uninfected control group, history of previous malaria episodes was associated with reduced perturbation of indirect bilirubin, total bilirubin, CCL2, CXCL10, IL-10 and IFN-γ." (PMID 34727121, 2021). "We also provide the evidence that, in turn, CXCL10 itself promotes malaria parasite growth." (PMID 34381047, 2021). "It was also determined that malaria outcomes could be altered based on the crosstalk between inflammatory cytokines (CXCL10, CCL3, IL-8, TNF-α, and IL-6) and Hb genotypes." (PMID 33424841, 2020). "Interestingly, among children with CM, those who died from a complication of malaria tended to have higher concentrations of IP-10/CXCL10 and IFN-γ than those who recovered." (PMID 32801995, 2020). "In the absence of malaria antigens, we observed a significant loss (P < 0.05) of the CXCL10 mRNA in PBMC-var compared to PBMC-WT." (PMID 33123155, 2020). "Furthermore, depletion of circulating endothelial progenitor cells during malaria pathogenesis is a function of heme-induced apoptosis mediated by CXCL-10 induction and toll-like receptor (TLR) activation." (PMID 31844087, 2019). "One aspect of malaria pathogenicity, the role of polymorphisms in human CXCL10, HO-1 and TLR genes have been reported but were not assessed here." (PMID 26555697, 2015). "This study acknowledges that depletion of EPC is an important facet of malaria pathogenesis and identifies heme, CXCL10, TLR4 and circulating EPC levels as potential biomarkers for identification of individuals at risk of developing severe forms of the disease." (PMID 26555697, 2015). "We have previously shown that high concentrations of free heme, and C-X-C motif chemokine 10 (CXCL10) in sera of malaria patients induce apoptosis in microvascular endothelial and neuronal cells contributing to vascular dysfunction, blood-brain barrier (BBB) damage and mortality." (PMID 26555697, 2015). "We hypothesized that EPC depletion during malaria pathogenesis is a function of heme-induced apoptosis mediated by CXCL10 induction and Toll-like receptor (TLR) activation." (PMID 26555697, 2015). "In addition, plasma levels of heme, heme oxygenase-1 (HO-1) and CXCL10 were significantly increased compared with non-malaria subjects." (PMID 26555697, 2015). "We tested the hypothesis that EPC depletion during malaria pathogenesis is a function of heme-induced apoptosis mediated by CXCL10 induction and toll-like receptor (TLR) activation." (PMID 26555697, 2015). "We hypothesized that CD34+-HSPC depletion during malaria pathogenesis is a function of heme-induced apoptosis mediated by induction of CXCL10 and TLR activation." (PMID 26555697, 2015). "Importantly, higher plasma and CSF levels of CXCL10 are seen in Ghanaian children with cerebral malaria, compared to those with severe malaria and non-malaria cases." (PMID 25177551, 2014). "In the present study, blood samples drawn from 135 Indian malaria patients (69 non-CM and 66 CM) were genotyped for CXCL10 promoter polymorphisms at position −135 and −1447." (PMID 24349056, 2013). "The genotype and allele frequencies of the −135G>A and −1447A>G polymorphisms in the promoter region of CXCL10 gene were studied in a cohort of 135 cases of malaria belonging to the CM and non-CM groups." (PMID 24349056, 2013). "Importantly, it has been reported that CXCL‐10 may act as a cue for growth acceleration in malaria parasites." (PMID 37697956, 2024). "Malaria related mortality is associated with significant deregulation of host inflammatory factors such as interferon-inducible protein 10, a member of the CXC or α-subfamily (CXCL10), and host angiogenic factors such as angiopoietin 1 (Ang-1) and angiopoietin 2 (Ang-2)." (PMID 35836234, 2022).
malaria (continued). "In addition to producing type I IFNs, DCs produce a wide range of pro-inflammatory cytokines, including TNF-α, IL-12, and IL-6, and chemokines, such as CXCL1, CXCL2, CCL2, CCL5, CXCL9, and CXCL10 in response to malaria parasites, and play crucial roles in malaria immunity and pathogenesis." (PMID 30619355, 2018). "Moreover, post mortem MIP-1β/CCL4, IL-8/CXCL8, and IP-10/CXCL10 levels were significantly elevated in cerebrospinal fluid (CSF) of fatal P. falciparum-induced CM cases when compared to fatal severe malarial anemia cases and non-malaria deaths." (PMID 28775960, 2017). "We report high plasma levels of proinflammatory cytokines and chemokines (IFNγ, TNF, IL-6, CCL2, CCL3, CCL4, CXCL10) in severe malaria patients compared to baseline uninfected follow-up, which matched that of Py infection in mice in which we could conduct a temporal analysis." (PMID 27792766, 2016). "This suggests that CM may be initiated or amplified by CXCL10 interaction with the brain cells resulting in changes in the blood-brain barrier and cerebrospinal fluid, which would allow other cytokines and malaria antigens to enter the brain compartment from which they would be normally excluded." (PMID 23630573, 2013). "For example, recent human and murine gene knock out studies suggest that plasma levels of Interferon inducible protein 10 (IP-10; CXCL10), soluble TNF receptor 2 (sTNF-R2) and soluble Fas (sFas) predict risk of malaria related mortality and may be potential biomarkers of CM severity." (PMID 21929748, 2011). "Chemokines such as CXCL10, MCP-1, and MIP-1β, which mediate leukocyte migration and inflammation, show elevated levels in malaria, reflecting disease severity." (PMID 39749215, 2024). "Increased IFN-γ, CXCL10, CX3CL1, IL-18, and IL-27 levels were observed in malaria coinfections compared to HIV monoinfection." (PMID 36716305, 2023). "This is a surprising result, as high levels of CXCL10 and CCL2 have been frequently reported as markers of severity and death during malaria and even CM." (PMID 36759905, 2023). "Distinct cytokine profiles in malaria and filariasis coinfections were IL-1Ra, IL-10, CXCL5, CXCL8, and CXCL10." (PMID 36716305, 2023). "Increased IFN-γ, IL-4, IL-10, IL-27, CXCL10, and CX3CL1 levels were observed in malaria monoinfection compared to HIV virus monoinfection." (PMID 36716305, 2023). "Relative involvement of CXCL10 and CXCL11 has been found to recruit inflammatory leukocytes of malaria-infected mice." (PMID 36239109, 2022). "Stimulation of ECs with plasma from malaria patients resulted in significantly increased levels of IL-11, CXCL5, CXCL8, CXCL10 and VEGF in comparison to stimulation of ECs using plasma from healthy controls." (PMID 34359826, 2021). "While children with asymptomatic malaria have increased IFNγ, TNF and IL-4 levels, IL-10 and CXCL10 were elevated in asymptomatically infected pregnant women." (PMID 33407502, 2021). "Comparable to the findings in this study, mDCs from malaria-naïve individuals secrete high levels of CXCL9 and CXCL10 in response to the parasite in vitro." (PMID 33407502, 2021). "Using information from the canonical coefficients, we found that the IFN pathway exhibited a relevant role in the discrimination of symptomatic malaria and controls, with CCL2 followed by CXCL10 and CXCL9 as the top markers." (PMID 34727121, 2021). "The second cluster of markers was composed by IFN-γ, creatinine, IL-1β, direct and indirect bilirubin, CXCL10 and IL-10, with heightened MDP values being observed in both the group of individuals with either asymptomatic or symptomatic malaria." (PMID 34727121, 2021). "Here, significantly elevated levels of CXCL10 and CXCL4 were found in patients who had died from CM compared to patients who had survived CM or patients with mild malaria." (PMID 34359826, 2021).
malaria (continued). "CXCL10, like VEGF and ANGPTL4, is present in significantly higher concentrations in culture supernatants of ECs stimulated with plasma from malaria patients compared to plasma from healthy individuals." (PMID 34359826, 2021). "Our studies showed that co-incubation of brain ECs with plasma from malaria patients resulted in significantly increased secretion of IL-11, CXCL5, CXCL10, VEGF and angiopoietin-like protein 4 (ANGPTL4)." (PMID 34359826, 2021). "For cytokines IL-6, IL-1RA, IL-10 and IL-11 and chemokines CXCL1, CXCL8, CXCL10, CCL3 and CCL2, significantly higher concentrations were found in plasma samples of malaria patients compared to healthy controls." (PMID 34359826, 2021). "The results indicate that differential expression of CXCL10, TNF-α, CCL2, IL-8, and IL-6 were tightly linked to hemoglobin genotype and severity of Plasmodium infection and that these cytokine levels may be predictive for susceptibility to severe malaria or SCD severity." (PMID 33424841, 2020). "CHI3L1 levels also correlated with markers of immune activation (CRP, sTREM-1, CXCL10/IP-10), endothelial activation (Ang-2, sICAM-1), and haemolysis (LDH, haem, haemopexin), pathways of injury that are well described in paediatric severe malaria." (PMID 29448936, 2018). "Malaria-induced MO-DCs possess a strong phagocytic activity, capacity to cross-present antigens to CD8+ T cells and express high levels of CXCL9, CXCL10 and the chemokine receptor CCR5." (PMID 27808089, 2016). "Circulating levels of CCL4 (also known as MIP-1β), CXCL10 (also known as IP-10), CXCL4 and CXCL8 have been found to be significantly elevated in CM cases compared with mild malaria cases or healthy control individuals." (PMID 24476686, 2014). "The relative involvement of the 3 CXCR3 chemokines (CXCL9, CXCL10 and CXCL11) in the recruitment of inflammatory leucocytes to the brain of malaria-infected mice has been extensively investigated." (PMID 24476686, 2014). "Since both human CM and murine ECM show major involvement of CXCL10 in pathogenesis of the disease, it is expected that sequence variations in the CXCL10 gene may result in altered expression of transcriptional and translational products thereby modulating CM progression in malaria patients." (PMID 24349056, 2013). "The results show that in early malaria, selected immune response-related genes were up-regulated including α β and γ interferon-related genes, as well as genes of IL-15, CD36, chemokines (CXCL10, CCL2, S100A8/9, CXCL9, and CXCL11), TRAIL and IgG Fc receptors." (PMID 24188121, 2013). "Our data indicate that Heme/HO-1, CXCL10/CXCR3 and STAT3 molecules as well as related signaling pathways play very important roles in the pathogenesis of severe malaria." (PMID 22479586, 2012). "Chemokine release is also associated with the malaria blood stage, but HZ alone did not induce the secretion of any of the chemokines investigated, CXCL8 (IL-8), CXCL9, CXCL10, CCL2 and CCL5." (PMID 40717771, 2025). "Although the exact mechanism of these chemokines in malaria pathogenesis is unknown, increased levels of chemokines such as CXCL9, CXCL10, and CXCL11 have been proposed as predictive markers for HIV disease progression." (PMID 36716305, 2023). "Global analysis of lung tissues and BALF of infected mice with MA-ARDS revealed elevated levels of the cytokines and chemokines also reported in the serum of severe malaria in humans mainly, IL-1, IL-6, IL-8, IL-10, TNF-α, IFN-γ, MCP-1/CCL2, MIP-2/CXCL2, IP-10/CXCL10, KC/CXCL1, VEGF, PIGF." (PMID 35677654, 2022). "This study provides the first evidence of Ang-1, Ang-2, and CXCL10 in saliva discriminating between malaria patients and non-malaria subjects." (PMID 35836234, 2022). "Malaria patients had lower saliva levels of Ang-1 (p = 0.009) and higher saliva levels of CXCL10 (p = 0.004) and Ang-2 (p = 0.001) compared to non-malaria subjects." (PMID 35836234, 2022).
malaria (continued). "In patients with severe malaria, platelets showed negative correlations with CXCL10, IL-6, IL-10 and IFN-γ." (PMID 36178979, 2022). "CXCL10 is a potent angiostatic and proinflammatory chemokine induced by IFN-γ, TNF, and other factors and has chemotactic activity for activated Th1 lymphocytes which have been demonstrated to be prognostic biomarkers in severe malaria." (PMID 35836234, 2022). "Culturing ECs with plasma from malaria patients (27 returning travellers) resulted in significantly increased secretion of IL-11, CXCL5, CXCL8, CXCL10, vascular endothelial growth factor (VEGF) and angiopoietin-like protein 4 (ANGPTL4) if compared to matching controls (22 healthy individuals)." (PMID 34359826, 2021). "CXCL10 has been shown to have a negative effect on the development of immunity and promotes severe outcomes in murine and human malaria." (PMID 33407502, 2021). "mDCs from malaria-exposed adults also secreted the Th1-associated chemokines CXCL9 (MIG) and CXCL10 (IP-10) as well as CCL2 but no CCL5." (PMID 33407502, 2021). "Based on our data CXCL10, TNF-α, CCL3, IL-8, and IL-6 may be investigated as potential markers to assess malaria severity and protection." (PMID 33424841, 2020). "In the experimental malaria model in mice, monocytes are the main sequestered leukocyte, inducing and aggravating brain inflammation by recruiting CD4+ and CD8+ T cells and also by the chemokine (C-X-C motif) ligand 10 (CXCL10) production." (PMID 32599864, 2020). "Circulating CXCL10, CCL3, IL-8, TNF-α, and IL-6 could be used as potential biomarkers for malaria severity among individuals with hemoglobinopathies." (PMID 33424841, 2020). "Significant correlations were identified for select individual genotypes with and without malaria between CXCL10, TNF-α and IL-6 with Hb, WBC, and RBC." (PMID 33424841, 2020). "Inflammatory chemokines CXCL10, CCL2, and CCL3 as well as cytokines, TNF-α, IL-8, and IL-6 were differentially expressed in individuals with different hemoglobin genotypes that were infected or uninfected with malaria parasites." (PMID 33424841, 2020). "Severe malaria patients exhibit high levels of serum pro-inflammatory cytokines (TNF, IL-1β, IL-6, IL-8, IL-12, IFNγ) and chemokines (CCL2, CCL5, CXCL9, CXCL10), and lower levels of regulatory cytokines (IL-10, TGFβ, PGE2) compared to those with mild and asymptomatic malaria." (PMID 27792766, 2016). "We have shown that decreased bioavailability of EPC in malaria patients is due, in part, to heme toxicity, mediated by expression of TLR4 and further exacerbated by an exaggerated host inflammatory response due to excess production of CXCL10." (PMID 26555697, 2015). "Moreover, cerebrospinal fluid levels of CXCL10, CXCL8 and CCL4 have been found to be significantly higher in children with CM compared with children with SMA and non-malaria-infected individuals." (PMID 24476686, 2014). "In the present study, we assessed the association between polymorphisms in the CXCL10 gene promoter region and the clinical status of malaria patients and identified the genetic basis of plasma CXCL10 production in CM patients compared to non-CM patients." (PMID 24349056, 2013). "In the group of individuals presenting with severe non-lethal malaria, parasitaemia displayed significant positive associations with TNF, sTNF-RI, IFN-γ, IL-10, CXCL9, CXCL10, SOD-1 and HO-1, while negatively correlated with the chemokines IL-8 and CCL2." (PMID 23433077, 2013). "Taken together, our data indicate that Heme/HO-1, CXCL10/CXCR3 and STAT3 molecules as well as related signaling pathways play very important roles in inflammation and organ damage in the pathogenesis of severe malaria." (PMID 22479586, 2012). "Furthermore, we previously showed that different sickle Hb genotypes with or without malaria parasites have different levels of CXCL10, CCL3, IL-8, TNF-α, and IL-6 in the blood." (PMID 37108709, 2023).
malaria (continued). "We evaluated the expression of CXCL10, TNF-α, CCL2, CCL3, IL-8, and IL-6 among 74 volunteers, from a pool of 923, with one (HbAS and HbAC), two (HbSS, HbSC, HbCC) and no (HbAA) copies of the Hb allele variant S and/or C with (+) and without (-) malaria." (PMID 33424841, 2020). "Here we show that during mouse malaria, splenic inflammatory monocytes differentiate into monocyte-derived dendritic cells (MO-DCs), which are CD11b+F4/80+CD11c+MHCIIhighDC-SIGNhighLy6c+ and express high levels of CCR5, CXCL9 and CXCL10 (CCR5+CXCL9/10+ MO-DCs)." (PMID 27808089, 2016). "Previous studies indicate that increased serum levels of free heme and CXCL10 limited the ability of the host to repair and regenerate damaged blood-brain barrier (BBB) components during development of severe malaria pathogenesis and were predictive of poor prognosis of severe malaria." (PMID 26555697, 2015). "In addition, age has been suggested to play a role in malaria pathogenesis, however, in our study age did not play a role in the expression of heme, CXCL10 and HO-1." (PMID 26555697, 2015). "However, for the malaria group, four distinct correlation patterns were observed; first pattern (CCL4, CCL2, CCL3, IL12 and IL2), second pattern (IL-17A, IL-1β, CCL11, IL4), third pattern (IL5, IL7, IL13), and fourth pattern (IL1RA, CXCL10, TNFα, IL2R, CXCL9, IL6)." (PMID 35811678, 2022). "The results showed that at days 2 and 4, IL-2 was significantly up-regulated in plasma of CXCL-10-/- than in WT, indicating that the absence of CXCL-10 promotes IL-2 expression during murine malaria and that it could play an important role in the pathogenesis of severe malaria." (PMID 21439091, 2011). "In the group of asymptomatic malaria participants, the Spearman correlation matrices revealed a unique negative correlation, between the MDP values of CXCL10 and IL-12p70." (PMID 34727121, 2021). "Pro-inflammatory chemokines (CXCL10, CCL2, and CCL3) and cytokines (TNF-α, IL-8, and IL-6) were reported to mediate severe malaria and SCD separately but have not been examined in SCD individuals infected with malaria." (PMID 33424841, 2020). "In malaria patients with HbS, serum levels of C-X-C motif chemokine ligand 10 (CXCL10), tumor necrosis factor-α (TNF-α), chemokine (C-C motif) ligand 2 (CCL2), interleukin-8 (IL-8), and interleukin-6 (IL-6) are lower compare to malaria patients without HbS." (PMID 40993672, 2025).